HIF1A (hypoxia inducible factor 1 subunit alpha)
Diseases named in the same sentence as HIF1A in open-access papers (continued):
Sharing a sentence is not in itself a finding about the gene and the disease.
COVID-19 (continued). "Furthermore, the disease severity significantly correlated with the degree of HIF1A upregulation early after full recovery from COVID-19." (PMID 38391913, 2024). "Indeed, we observed a significant increase in placental lipid peroxidation and HIF-1α expression in all COVID-19-positive women." (PMID 39768279, 2024). "Also, high HIF-1α levels were detected in peripheral blood monocytes of COVID-19 patients and infected cells." (PMID 38914619, 2024). "Moreover, in COVID-19 patients who develop local hypoxia, HIF-1α nuclear translocation stimulates VEGF production, leading to vascular leakage in endothelial capillary cells." (PMID 36983445, 2023). "The PPI network analysis exhibits that numerous genes, including IL-6, TNF-α, MAPK3, MAPK1, AKT1, mTOR, HIF1A, HSP90AA1, EGFR, CASP3, etc., are implicated in the pathogenicity of COVID-19 disease and also in the anti-COVID-19 effects of Meliae cortex’s key active phytonutrients." (PMID 36817449, 2023). "This discrepancy between the beneficial and harmful effects of HIF-1α activation in COVID-19 may be due to cell-specific HIF signaling during SARS-CoV2 infection." (PMID 36983445, 2023). "Patients with severe COVID-19 may also see an increase in the degradation of FOXP3 proteins because the hypoxic lung environment activates HIF1A, which is involved in aerobic glycolysis." (PMID 37521843, 2022). "This leads to the hypothesis that hypoxia could have a beneficial effect on the molecular crosstalk that regulates the severity of COVID-19 through HIF-1α." (PMID 36091390, 2022). "In severe COVID-19 cases, preventing HIF1α degradation could worsen the immune response, of which the implications are unknown and could be severe." (PMID 36324747, 2022). "As observed in the severe vs. mild comparison, hypoxia related pathways were identified as enriched in severe COVID-19 including Hypoxia Signalling in the Cardiovascular System (z-score = 1.732; BH p-value = 4.571 × 10–02) and HIF1α Signalling (z-score = 2.109; BH p-value = 1.202 × 10–07)." (PMID 35844004, 2022). "Patients with COVID-19 may have respiratory failure, which may result in hypoxemia and, consequently, peripheral tissue ischemia, explaining the increase in HIF-1α." (PMID 36439786, 2022). "Because both LDH and FIB are hypoxia-regulated genes, we also investigated the expression of the hypoxia marker genes EPO, GLUT1, and HIF-1α in whole blood samples of the two COVID-19 patient cohorts (Ward/CoV-2 and ICU/CoV-2) and compared them to the healthy subjects." (PMID 36611805, 2022). "HIF-1α/renalase axis presumably functions with the purpose of compensation, and/or adaptation to a low oxygen environment, supporting the possible link of renalase and COVID-19-related ARDS." (PMID 36132227, 2022). "Besides activation of the NLRP3 inflammasome and HMGB1, hypoxia-inducible factor-1α (HIF-1α) signaling pathway is also elevated in elderly patients with COVID-19." (PMID 35356515, 2022). "It is conceivable that the increased activity of SERPINF1 and THBS2 together with the high activity of HIF1A contribute to favoring of intussusceptive angiogenesis over conventional sprouting angiogenesis in the hypoxic environment of COVID-19 pulmonary involvement." (PMID 35163504, 2022). "A study of PPG patients that are followed in specialized centres worldwide would be informative; if a protective effect is noted, the implication of HIF1α in COVID-19 could open ways of therapeutic interventions." (PMID 34684070, 2021). "It has been suggested that increased levels of ACE2 positively correlate with COVID-19, thus the stabilization of HIF1α which in turn, down regulates the ACE2 gene, could improve the outcomes in COVID-19 patients." (PMID 33345622, 2021). "Thus, further study is still required to clarify the role of PI3K/Akt/mTOR pathway in regulating HIF-1α expression in COVID-19." (PMID 34277453, 2021).
COVID-19 (continued). "In patients with COVID-19, pneumonia and vascular permeability are related to the elevated thrombosis, which is stimulated by a hypoxic state in which the hypercoagulability is increased along with HIF-1α expression." (PMID 34484241, 2021). "In conclusion, in the present study, we have demonstrated the expression of HIF1α and its transcriptionally regulated genes, in myeloid cells, including both mature and immature subsets, present in peripheral blood of critically ill COVID-19 patients." (PMID 33345622, 2021). "Hence, Notch activation in COVID-19 patients is likely directly exacerbating the hypoxic events by cooperating with HIF-1α in addition to promoting structural defects in the air sacs." (PMID 34124207, 2021). "Furthermore, the use of HIF-1α inhibitors for the treatment of patients infected with COVID-19 has recently been highlighted." (PMID 33868294, 2021). "Therefore, in the present work we carried out scRNAseq to identify the cell populations present in critically ill COVID-19 patients and to determine the expression of hypoxia-induced factor 1α (HIF1α) and its related genes." (PMID 33345622, 2021). "In this study, based on RNA sequencing and clinical specimens’ analyses, we initially showed that the expressions of HIF-1α and pro-inflammatory cytokines were induced in COVID-19 patients, and elderly patients display excessive inflammatory responses that were associated with high mortality." (PMID 34408131, 2021). "In conclusion, persons dwelling in high altitudes, or patients with PPG, may be protected to a degree from COVID-19, by means of HIF1α activation." (PMID 34684070, 2021). "Increased expression of HIF-1α mRNA has also been reported in myeloid blood cells from critically ill COVID-19 patients, along with the expression of other genes, TLR2 and TLR4, which could be involved in SARS-CoV-2 sensing." (PMID 34835108, 2021). "In this scenario, promoting systemic HIF-1α activity through pharmacological intervention in severe COVID-19 patients might be detrimental." (PMID 34013835, 2021). "Hypoxia-inducible factor 1α (HIF-1α) is involved in the activation of pro-inflammatory cytokine expression and the subsequent inflammatory process, which makes it a potential molecular marker of the severity of COVID-19." (PMID 34803696, 2021). "However, the only research focus on the PI3K/Akt/mTOR/HIF-1α in COVID-19 pathogenesis is in contradiction to the evidence of overexpressed HIF-1α in other studies." (PMID 34277453, 2021). "Further to this, inhibition of ACE2 by HIF-1α could provide a novel method of treating COVID-19 with IHP." (PMID 35003073, 2021). "In COVID-19 patients, hypoxia and ROS both promote the transcription and stabilization of HIF-1α." (PMID 34277453, 2021). "As proposed by others, the role of HIF-1a in COVID-19 needs further attention." (PMID 33841435, 2021). "Furthermore, the possible effect of the HIF-1α on the COVID-19 pathogenesis and ARDS symptoms in patients can be explained through its relevant role in other component of the immune system including the complement system." (PMID 33139969, 2020). "Moreover, COVID-19-related microvascular dysfunction and tissue hypoxia have also been reported, which could further promote HIF-1α stabilization." (PMID 41202111, 2025). "Therefore, they suggested that stimulation of autophagy and HIF-1α by COVID-19 may be a marker for AML patients, especially those with FLT3-ITD mutations." (PMID 38360719, 2024). "Increased MK expression has been reported during hypoxia, as HIF1-α binds to hypoxia-responsive elements located in the MK promoter, suggesting that the hypoxia-driven inflammatory misalignment by MK may contribute to COVID-19." (PMID 37835544, 2023). "Thus, stabilizing HIF-1α could be one of the ways to act on the outcome of COVID-19 patients, reducing hypoxia and acting on ACE2 expression." (PMID 36983445, 2023).
COVID-19 (continued). "In addition, we hypothesized that the expression of both CD147 and CyPA could be increased by Hypoxia-inducible Factor-1 alpha (HIF-1α) activation during hypoxic conditions that occurred during COVID-19." (PMID 37016434, 2023). "Clustering and shared upregulation of glycolytic enzyme encoding genes GALM, GAPDH, GPI, and ALDOA together with HIF1A, and transcripts regulating exhaustion (TIGIT and LAG3) suggested that hypoxia/anaerobic axis is associated with impaired CD8+TM function in COVID-19 BALF." (PMID 37029220, 2023). "Based on the results of core signaling analyses and considering relative protein/gene expression levels as compared with normal nasopharyngeal tissues, we choose TNF, NFkB, and HIF1A as common biomarkers (drug targets) of infections pathogenesis in both COVID-19-associated ARDS and non-viral ARDS." (PMID 35409008, 2022). "In these circumstances, stabilization of HIF-1α may worsen the pathogenesis of COVID-19." (PMID 36140358, 2022). "Thus, stabilization of HIF-1α may improve the outcome of COVID-19 by decreasing hypoxia and acting on ACE2 expression." (PMID 36091390, 2022). "However, some authors offered alternative hypotheses of COVID-19 pathogenesis, presuming that HIF-1α activation occurs early during the course of the disease, initiating a few meaningful pathways." (PMID 36132227, 2022). "In addition, COVID-19 may increase the expression of hypoxia-inducible factor-1 (HIF-1α), a nuclear protein first seen in cells cultured in oxygen-deprived environments." (PMID 36439786, 2022). "Similarly, activation of COX2 and HIF-1α in COVID-19 has been shown to upregulate the antiapoptotic antiproliferative microenvironment (BCL2, BNIP3) and M1 immune system {nuclear factor kappa B (NFKB), Egl-9 family hypoxia inducible factor 3 (EGLN3), CXCL8, TNF-α, and IL-6 }." (PMID 36671699, 2022). "Moreover, the decreased oxygen saturation in blood of severe COVID-19 patients might activate HIF-1a signaling in circulation and contribute to excessive neutrophil function in COVID-19 patients." (PMID 33841435, 2021). "Furthermore, Notch activation is known to exacerbate hypoxic events by cooperating with HIF-1α in addition to enhancing structural defects in the air sacs in the lungs, which together may contribute to enhanced lung pathology in COVID-19 patients." (PMID 34124207, 2021). "Such an implication of HIF1α vis-à-vis COVID-19 could open ways of therapeutic interventions." (PMID 34684070, 2021). "Therefore, targeting HIF-1α may reduce cytokine storm and provide a great therapeutic treatment of COVID-19." (PMID 33002109, 2020). "Therefore, HIF-1α inhibition through pharmacological strategies might provide a new approach to aid the treatment of patients affected with COVID-19." (PMID 33139969, 2020). "Furthermore, the hypoxic environment in the lung of severe COVID-19 patients may activate HIF-1α, which mediates aerobic glycolysis, and thereby promotes the degradation of FOXP3 proteins." (PMID 33178221, 2020). "Another study investigated the shared pathways involved in the comorbidity of COVID-19 and COPD, identifying critical genes, such as CCL2, MMP9, IL1A, and HIF1A, which play pivotal roles in immune responses, angiogenesis, and inflammation." (PMID 39997467, 2025). "In contrast to previous studies that report HIF1A upregulation in PBMCs, we observed significantly reduced HIF1A and GLUT1 expression in NK cells from patients with severe COVID-19." (PMID 40927375, 2025). "However, oxygen supplementation alone may be insufficient to fully correct persistent, localized hypoxia in severely damaged lung areas post-ARDS, sustaining HIF-1α-driven hypoxic signaling and complicating the distinction between hypoxic and inflammatory contributions to severe COVID-19 pathology." (PMID 40362439, 2025). "This synergy is exacerbated in COVID-19, where hypoxemia and cytokine storms jointly inhibit prolyl hydroxylase (PHD) activity, preventing HIF-1α degradation." (PMID 40362439, 2025).
COVID-19 (continued). "The upregulation of genes involved in hypoxia (HIF1α) and metabolic adaptation (NFE2L2) in macrophages from severe COVID-19 cases indicates a metabolic reprogramming that supports their inflammatory function." (PMID 39928675, 2025). "In our study, we assessed the expression of various HIF isoforms (HIF-1α, HIF-2α, HIF-3α) and found that the expression of all subunits significantly increased in COVID-19 patients." (PMID 40702494, 2025). "Elucidating how metabolic sensors, such as HIF-1α, GLUT1, SIRT1, and AMPK, influence NK cell function in COVID-19 will enhance our understanding of disease pathogenesis and serve as a basis for novel therapeutic approaches in patients with COVID-19." (PMID 40927375, 2025). "In patients with mild and moderate COVID-19, HIF-2α expression increased the most (6-fold and 10.6-fold relative to controls), followed by HIF-1α (4.3-fold and 8.2-fold), and to a lesser extent, HIF-3α (6.2-fold and 7.1-fold)." (PMID 40702494, 2025). "The interplay between HIF-1α and SARS-CoV-2 infectivity is increasingly recognized as a critical axis in COVID-19 pathophysiology." (PMID 40362439, 2025). "Several studies showed that the up-regulation and participation of hypoxia-inducible factor-1α (HIF-1α) relate to inflammation, immunometabolism, and TLR in bronchoalveolar cells of critically severe COVID-19 patients." (PMID 38914619, 2024). "For example, individuals with moderate COVID-19 demonstrated lower levels of FOSL2, MAX, MAFB, IRF1, RUNX3, and HIF1A in CD14 and CD16 monocytes from other cohorts." (PMID 39712003, 2024). "Integrating top functional and topological significance targets, we identified that the alpha subunit of HIF-1α was the only overlap target from both functional and topological views as the key target of QFPDD for treating COVID-19 reduced HMI." (PMID 38476329, 2024). "Specifically, we found a set of 89 DE genes in COVID-19 macrophages from all three organs, including PLCG2, HIF1A, ACTB, and JUND." (PMID 37830426, 2023). "The top ten anti-COVID-19 core targets, AKT1, TNF, HSP90AA1, IL-6, mTOR, EGFR, CASP3, HIF1A, MAPK3, and MAPK1, were chosen for molecular docking studies with the Meliae cortex’s key active phytonutrients determined in section 3.7." (PMID 36817449, 2023). "Since HIF-1α is a critical promoter of both SARS-CoV-2 infection and inflammatory response, it is suggested as a viable therapeutic target for COVID-19 and virus-induced inflammatory infection." (PMID 38049897, 2023). "Four proteins (CTNNB1, HIF-1α, VEGF and ANGPT) related to the 22 mRNAs described for COVID-19 were analyzed." (PMID 36992415, 2023). "The top three Meliae cortex’s key active phytonutrients were further analyzed for molecular docking with the top ten anti-COVID-19 core targets, including AKT1, TNF, HSP90AA1, IL-6, mTOR, EGFR, CASP3, HIF1A, MAPK3, and MAPK1." (PMID 36817449, 2023). "In COVID-19 patients, we suspect that the presence of SARS-CoV-2 virus in the heart has a similar effect on HIF1α stabilization." (PMID 36324747, 2022). "A recent report using RNA sequencing and clinical sample analyses highlighted the role of HIF-1α expression and SARS-CoV-2 ORF3a-mediated mitochondrial dysfunction in the infection and pro-inflammatory responses to COVID-19." (PMID 36614003, 2022). "Here, we review the evidence for a link between HIF-1α, ACE2 and AT1R expression, and the incidence/severity of COVID-19." (PMID 36091390, 2022). "HIF-1α signaling pathway was involved in SARS-CoV-2 virus infection and subsequent inflammatory response, often leading to poor prognosis in COVID-19 patients." (PMID 35677450, 2022). "HIF-1α activates glycolysis and inflammatory response, which implies the effects of HIF-1α on the pathogenesis of COVID-19." (PMID 36406408, 2022). "SARS-CoV-2 also upregulates glycolysis in host immune cells via HIF1α, as evidenced by elevated pyruvate, pyruvate kinase, and lactate dehydrogenase (LDH) in COVID-19 patients." (PMID 35401519, 2022).
COVID-19 (continued). "Thus, melatonin may reduce the damage resulting from COVID-19-mediated septicemia by quelling HIF-1α, suppressing NF-ҝB, inhibiting the inflammasome and converting pro-inflammatory M1 macrophages to anti-inflammatory M2 macrophages while also reversing Warburg-type metabolism." (PMID 35187603, 2022). "The up-regulation and participation of HIF1α in relevant events such as inflammation, immunometabolism, and TLR supports its use as molecular marker for COVID-19 severity and as a potential candidate for targeted therapy." (PMID 33345622, 2021). "Thus, HIF1A inhibitors may interfere with processes that promote COVID-19 pathogenesis." (PMID 34975885, 2021). "This is supported by ex-vivo COVID-19 studies show that succinate levels and nuclear translocation of both HIF1α and PKM2 positively correlate with COVID-19 disease severity." (PMID 34240083, 2021). "Notable UPRs of COVID-19 blood included IFNA, IFNG, multiple growth factors and ligands, HIF1A, CSF1 and CSF2." (PMID 33782412, 2021). "Indeed, hypoxia is a primary pathophysiological feature in severe COVID-19 and HIF1A is speculated to contribute largely to the CRS by activating and preventing turnover of immune cells including macrophages and neutrophils, which secrete large amounts of inflammatory cytokines." (PMID 34163359, 2021). "In addition, HIF1A has also been reported to promote SARS-CoV-2 infection and exacerbate the inflammatory response in COVID-19, and SARS-CoV-2-induced cytokine storms are regarded as a major pathological feature of COVID-19." (PMID 41411324, 2025). "Monocytes and B cells from the patient with asymptomatic COVID-19 (clinical score of 0) showed no significant upregulation of HIF1A in week 2 compared to both later time points." (PMID 38391913, 2024). "We then compared CD3+ cells isolated from COVID-19-infected subjects vs. healthy controls and found increased expression of activation markers including CD69, CD83, ICOS, RGS1 as well as other stress related genes including HIF1A, ATF4, NFKB1, and PR1." (PMID 36881624, 2023). "HIF-1A and anaerobic glycolysis gene expression was strongly correlated with reduced expression of the OXPHOS and TCA cycle genes in these EC subsets from severe COVID-19." (PMID 37029220, 2023). "In our research, the results showed no significant changes in the plasma level of HIF-1α in patients with OA, including patients who recovered from COVID-19." (PMID 37484856, 2023). "In addition, cluster 1 confirms the existence of the top ten potential anti-COVID-19 core targets (AKT1, TNF, HSP90AA1, IL-6, mTOR, EGFR, CASP3, HIF1A, MAPK3, and MAPK1); consequently, the results of the PPI and cluster network analyses are congruent." (PMID 36817449, 2023). "However, these apoptotic gene signatures were characterized by distinct DEGs expressed in the COVID-19(+) TV (BCLAF1, BCL2L1) and COVID-19(-) PU control groups (BAD, ACIN1, HIF1A)." (PMID 37026002, 2023). "In this scenario, the combination of HIF-1α activation and LEF1-AS1 decrease may both contribute to the dysregulation of myeloid cells in COVID-19 patients." (PMID 37884975, 2023). "Indeed, recent data imply an important role of HIF-1α in promoting SARS-CoV-2 infection and inducing pro-inflammatory responses to COVID-19." (PMID 35330457, 2022). "The observed elevated levels of LDH protein and increased expression of HIF-1α and GLUT1 in the ICU COVID-19 patients likely correlate with an enhanced glucose utilization that could be evidence of the hypoxic conditions caused by the virus infection." (PMID 36611805, 2022). "Interestingly, the mRNA levels of HIF-1α and GLUT1 genes were also found significantly elevated in the whole blood samples of the ICU COVID-19 patients." (PMID 36611805, 2022). "Interestingly, accumulation of cytosolic succinate resulted in decreased breakdown of HIF-1α and therefore enhanced the cytosolic levels of HIF-1α in COVID-19 neutrophils." (PMID 35251008, 2022).